MGME1 (mitochondrial genome maintenance exonuclease 1)
Description:
Metal-dependent single-stranded DNA (ssDNA) exonuclease involved in mitochondrial genome maintenance. Has preference for 5'-3' exonuclease activity but is also capable of endonuclease activity on linear substrates. Necessary for maintenance of proper 7S DNA levels. Probably involved in mitochondrial DNA (mtDNA) repair, possibly via the processing of displaced DNA containing Okazaki fragments during RNA-primed DNA synthesis on the lagging strand or via processing of DNA flaps during long-patch base excision repair. Specifically binds 5-hydroxymethylcytosine (5hmC)-containing DNA in stem cells.
Synonyms: C20orf72; DDK1; bA504H3.4; MTDPS11
Tractability: Small molecule: a structure with a bound ligand is known. PROTAC: ubiquitination databases record sites on it.
Gene: Protein-coding gene on chromosome 20 (17,968,213 to 17,991,136, forward strand). Ensembl gene ENSG00000125871.
Subcellular location: Mitochondrion
Subcellular location (Human Protein Atlas): Mitochondria
Pathways (Reactome):
DNA Replication: Strand-asynchronous mitochondrial DNA replication
Gene Ontology:
Molecular function: 5'-flap endonuclease activity; protein binding; single-stranded DNA 5'-3' DNA exonuclease activity; single-stranded DNA exodeoxyribonuclease activity
Biological process: mitochondrial DNA replication; mitochondrial DNA repair; DNA repair
Cellular component: mitochondrion; mitochondrial matrix
Genetic constraint (gnomAD): Loss-of-function variants: 27 observed, 39.97 expected, observed/expected ratio (o/e) 0.68, 90% interval 0.5 to 0.93. The upper end of that interval is the gene's LOEUF score, 0.93, which puts it in group 3 of 6, group 1 being the genes least tolerant of losing a copy. Missense variants: 383 observed, 421.1 expected, observed/expected ratio (o/e) 0.91, 90% interval 0.84 to 0.99. Synonymous variants: 133 observed, 154.02 expected, observed/expected ratio (o/e) 0.86, 90% interval 0.75 to 1.
Gene-disease validity (ClinGen):
ClinGen rates the evidence that MGME1 causes each of these diseases.
mitochondrial disease (autosomal recessive): Definitive.
Homologues: Orthologues: chimpanzee MGME1 (99% identical), macaque MGME1 (96% identical), pig MGME1 (80% identical), dog MGME1 (79% identical), rat Mgme1 (72% identical), mouse Mgme1 (70% identical), guinea pig MGME1 (69% identical), rabbit MGME1 (67% identical), tropical clawed frog mgme1 (56% identical), zebrafish mgme1 (48% identical), Caenorhabditis elegans C27H6.9 (19% identical).
Diseases named in the same sentence as MGME1 in open-access papers:
MGME1 is named in the same sentence as 42 diseases in open-access papers, as found by Europe PMC text mining. Sharing a sentence is not in itself a finding about the gene and the disease. The quoted sentences say what the papers report.
glioma (2 papers, 2022 to 2023). A benign or malignant brain and spinal cord tumor that arises from glial cells (astrocytes, oligodendrocytes, ependymal cells). "Afterwards, we further examined the prognostic value of MGME1 in LGGs using three independent cohorts, including the TCGA cohort (n = 477), the Chinese Glioma Genome Atlas (CGGA) cohort (n = 170), and the GSE16011 cohort (n = 102)." (PMID 37166417, 2023).
Mitochondrial myopathy (2 papers, 2022 to 2025). "Mutations in mitochondrial genes, such as MT-ATP6, and nuclear genes, such as MGME1 [MIM:615076] and RRM2B [MIM:604712], which are essential for mitochondrial function, can cause mitochondrial myopathy [MIM:500009], sometimes accompanied by ptosis." (PMID 40410591, 2025).
Alzheimer disease (1 paper, 2025). A progressive, neurodegenerative disease characterized by loss of function and death of nerve cells in several areas of the brain leading to loss of cognitive function such as memory and language. "Using bioinformation approaches, we discovered HIBCH and MGME1 as novel biomarkers to identify the underlying processes of mitochondrial dynamics that cause impaired mitochondrial function in Alzheimer's disease, and HIBCH was linked to Tau metabolism." (PMID 40286336, 2025). "MGME1 was identified among 68 signature genes distinguishing Alzheimer's disease (AD) from Parkinson's disease (PD) and healthy controls." (PMID 40286336, 2025).
anemia (1 paper, 2018). A reduction in the number of red blood cells, the amount of hemoglobin, and/or the volume of packed red blood cells. "Importantly, the anemia of Mgme1−/− mice is much milder than the anemia in mtDNA mutator mice despite the observation that Mgme1−/− mice have much higher levels of subgenomic deleted mtDNA than mtDNA mutator mice." (PMID 29572490, 2018).
cardiomyopathy (1 paper, 2022). A disease of the heart muscle or myocardium proper. "Human patients with MGME1 deficiency were reported to have an adult onset, multisystem mitochondrial disorder including progressive external ophthalmoplegia (PEO), muscle wasting, muscle weakness, exercise intolerance, cerebellar atrophy, cerebellar ataxia and cardiomyopathy." (PMID 35533204, 2022).
External ophthalmoplegia (1 paper, 2018). Paralysis of the external ocular muscles. "Mutations in MGME1-coding gene lead to severe mitochondrial syndromes characterized by external ophthalmoplegia, emaciation, and respiratory failure in humans." (PMID 30247721, 2018).
gastric cancer (1 paper, 2023). A primary or metastatic malignant neoplasm involving the stomach. "Studies on MGME1 suggest a direct involvement in cancer development and progression, and finally upregulation of the EPH8A gene expression was associated with a poor prognosis in ovarian, oral tongue, and gastric cancers." (PMID 37444464, 2023).
keratinocyte carcinoma (1 paper, 2023). A skin cancer arising from the keratin-producing cells of the epidermis. "Using whole exome sequencing data, we performed groupwise tests for rare missense variants in our dataset and found robust associations (p < 10−6, Burden Zeggini test) between MC1R, EPHA8, EPO, MYCT1, ADGRG3, and MGME1 and keratinocyte cancer." (PMID 37444464, 2023).
kidney inflammation (1 paper, 2022). "Ageing Mgme1-/- mice develop kidney inflammation, tubulointerstitial fibrosis and glomerular changes leading to nephrotic syndrome." (PMID 35533204, 2022).
mitochondrial DNA depletion syndrome type 11 (1 paper, 2025). "According to clinical study, mutations in the MGME1 gene may cause mitochondrial DNA depletion syndrome type 11 (MTDPS11)." (PMID 40286336, 2025).
mtDNA depletion syndromes (1 paper, 2022). "Many of the significant genes have known mitochondrial functions, notably the mtDNA transcription factor TFAM (p = 1.09 × 10–29) and mitochondrial exonuclease MGME1 (p = 5.87 × 10–23), genes known as causal for mtDNA depletion syndromes." (PMID 34859289, 2022).
progeria (1 paper, 2018). "Mice with MGME1 deficiency accumulate a long linear subgenomic mtDNA species, similar to the one found in mtDNA mutator mice, but do not develop progeria." (PMID 29572490, 2018).
viral infection (1 paper, 2019). "Our data further identified numerous ribonuclease and deoxyribonuclease genes with unknown roles in viral infection such as Dnase1l3, Dclre1c, Rexo1, Dxo, and Mgme1." (PMID 31057555, 2019).
tumor (9 papers, 2015 to 2024). "Therefore, we comprehensively studied the relationships between MGME1 expression, clinical characteristics, tumor immunity, gene mutations, prognosis, biological functions, and treatment responses of LGG patients." (PMID 37166417, 2023). "The immune-related signatures, infiltration of immune cells, immune checkpoint genes (ICPGs), copy number alteration (CNA), tumor mutation burden (TMB), and treatment responses of LGG patients were associated with the expression of MGME1." (PMID 37166417, 2023). "The ESTIMATE algorithm showed that MGME1 expression was positively correlated with estimation, immune scores, and stromal but negatively correlated with tumor pureness in the TCGA and CGGA cohorts." (PMID 37166417, 2023). "Given the value of genomic variations in tumor immune regulation and infiltration, we used CNA and somatic mutation analysis to distinguish the differential genomic mutations in the low-MGME1 and high-MGME1 expression subgroups." (PMID 37166417, 2023).
cancer (7 papers, 2010 to 2024). A tumor composed of atypical neoplastic, often pleomorphic cells that invade other tissues. "We also probed the association between TMB and MGME1 expression in 33 cancers." (PMID 37166417, 2023). "In effect, the high-MGME1 expression subtype was more susceptible to the anti-cancer drugs." (PMID 37166417, 2023). "We exploited a univariant Cox regression analysis to inspect the association between MGME1 expression and OS and determine the prognostic significance of MGME1 in 33 cancer types." (PMID 37166417, 2023). "Comparison of the pan-oncogene expression data obtained from the TCGA and GTEx databases manifested that MGME1 was abnormally upregulated in various cancers." (PMID 37166417, 2023). "The high MGME1 expression was relevant to the lower inhibitory centration (IC50) of these anti-cancer drugs." (PMID 37166417, 2023). "Therefore, these anti-cancer drugs may be used for chemotherapy for patients with LGG with high MGME1 expressions in the future." (PMID 37166417, 2023).
mitochondrial disease (4 papers, 2018 to 2023). "Mutations in the mitochondrial genome maintenance exonuclease 1 (MGME1) gene were recently reported in mitochondrial disease patients." (PMID 29572490, 2018). "With the exception of SSBP1, a key component of the mitochondrial replication fork, to date, all nuclear genes directly involved in mtDNA replication (POLG, POLG2, TWINKLE, RNASEH1, DNA2, MGME1) have been associated with mitochondrial disease, mtDNA depletion, and/or mtDNA deletion." (PMID 31550237, 2020). "The majority of the core proteins of the mtDNA replication and expression machinery are dedicated mitochondrial proteins, with pathological variants resulting solely in mitochondrial disease phenotypes, including POLG, POLG2, TWINKLE, MGME1 and POLRMT." (PMID 37013609, 2023).
infection (2 papers, 2024 to 2025). The state of being infected such as from the introduction of a foreign agent such as serum, vaccine, antigenic substance or organism. "This is substantiated by evidence linking MGME1 mutations to pathological accumulations of mtDNA deletions, which amplify susceptibility to infection‐triggered chronic inflammation—a hallmark of neurodegenerative progression." (PMID 40286336, 2025). "Five days post infection with rAd-MitoScaI, C57WT and Mgme1KW mice both had a marked decrease in mtDNA levels (Nd1 and D-Loop), nearly to 0%, while Mgme1 KK kept around 30% of their baseline mtDNA levels which fell in line with the results seen in cultured cells." (PMID 38432635, 2024).
gastrointestinal disease (1 paper, 2024). A disease that occurs in the gastrointestinal system, excluding the hepatobiliary system. "Recessive MGME1 variants cause PEO, ptosis, and marked myopathy with respiratory weakness in childhood or early adulthood, with mtDNA depletion or multiple deletions, and may cause severe emaciation due to gastrointestinal disease." (PMID 38804971, 2024).
retinopathy (1 paper, 2022). "We report that Mgme1 knockout mice develop a dramatic phenotype as they age and display progressive weight loss, cataract and retinopathy." (PMID 35533204, 2022). "In addition, we report that loss of MGME1 leads to age-associated pathology manifested as progressive weight loss, cataract and retinopathy." (PMID 35533204, 2022). "In addition, the Mgme1 knockout mice develop cataracts and retinopathy at 65–70 weeks of age." (PMID 35533204, 2022).
MGME1 also shares sentences with these, for which no sentence is quoted: breast carcinoma (4 papers); colon cancer (2); ovarian carcinoma (2); aortic valve calcification (1); cerebellar ataxia (1); Cerebellar atrophy (1); Cerebral ischemia (1); chondrosarcoma (1); chronic kidney disease (1); diabetes (1); endometriosis (1); Hypertension (1); myeloma (1); myopathy (1); Nephropathy (1); nephrotic syndrome (1); osteoporosis (1); progressive external ophthalmoplegia (1); prostate carcinoma (1); ptosis (1); renal failure (1); respiratory failure (1); Stroke (1).